DIXDC1 (DIX domain containing 1)
Description:
Positive effector of the Wnt signaling pathway; activates WNT3A signaling via DVL2. Regulates JNK activation by AXIN1 and DVL2.
Synonyms: CCD1; KIAA1735; Dixin
Tractability: PROTAC: UniProt records ubiquitination sites on it; ubiquitination databases record sites on it; its protein half-life has been measured.
Gene: Protein-coding gene on chromosome 11 (111,927,144 to 112,022,653, forward strand). Ensembl gene ENSG00000150764.
Subcellular location: Cell junction, focal adhesion; Cytoplasm, cytoskeleton, stress fiber; Cytoplasm; Cytoplasm (Isoform 2)
Subcellular location (Human Protein Atlas): Cytosol
Gene Ontology:
Molecular function: gamma-tubulin binding; protein binding; protein domain specific binding
Biological process: canonical Wnt signaling pathway; cell proliferation in forebrain; cerebral cortex cell migration; cerebral cortex radially oriented cell migration; forebrain ventricular zone progenitor cell division; modification of postsynaptic actin cytoskeleton; negative regulation of neuron differentiation; positive regulation of Wnt signaling pathway; regulation of actin cytoskeleton organization; regulation of microtubule cytoskeleton organization; Wnt signaling pathway
Cellular component: cytoplasm; cytosol; focal adhesion; glutamatergic synapse; postsynapse; stress fiber
Genetic constraint (gnomAD): Loss-of-function variants: 58 observed, 92.22 expected, observed/expected ratio (o/e) 0.63, 90% interval 0.51 to 0.78. The upper end of that interval is the gene's LOEUF score, 0.78, which puts it in group 3 of 6, group 1 being the genes least tolerant of losing a copy. Missense variants: 745 observed, 824.46 expected, observed/expected ratio (o/e) 0.9, 90% interval 0.85 to 0.96. Synonymous variants: 263 observed, 298.46 expected, observed/expected ratio (o/e) 0.88, 90% interval 0.8 to 0.98.
Homologues: Orthologues: chimpanzee DIXDC1 (99% identical), macaque DIXDC1 (98% identical), dog DIXDC1 (95% identical), guinea pig DIXDC1 (92% identical), mouse Dixdc1 (92% identical), rat Dixdc1 (88% identical), rabbit DIXDC1 (86% identical), tropical clawed frog dixdc1 (68% identical), zebrafish dixdc1b (57% identical), zebrafish dixdc1a (38% identical), Caenorhabditis elegans dsh-1 (12% identical), Drosophila melanogaster dsh (11% identical), and 2 more. Paralogues in human: DVL1 (16% identical), DVL2 (15% identical), DVL3 (15% identical).
Diseases named in the same sentence as DIXDC1 in open-access papers:
DIXDC1 is named in the same sentence as 27 diseases in open-access papers, as found by Europe PMC text mining. Sharing a sentence is not in itself a finding about the gene and the disease. The quoted sentences say what the papers report.
Anxiety (3 papers, 2017 to 2023). Intense feelings of nervousness, tension, or panic often arise in response to interpersonal stresses. "Knockout mice for DIX domain containing-1, an intracellular Wnt/β-catenin signal pathway protein, exhibit symptoms of anxiety, depression, and social behavior." (PMID 29200666, 2017). "Suppressed β-catenin has also been found in mice lacking DIX domain containing-1 (DIXDC1), a protein involved in the intracellular Wnt/β-catenin signaling pathway, which exhibit abnormal anxiety, depression, and social deficits." (PMID 37009120, 2023).
breast carcinoma (3 papers, 2019 to 2022). "It has been reported that Wnt signaling is related to bone metastasis in breast cancer and that DIXDC1 can promote the metastasis of cancer cells by activating the Wnt signaling pathway." (PMID 31213036, 2019).
acute myeloid leukaemia (2 papers, 2021 to 2022). "There is growing evidence suggesting that DIXDC1 has carcinogenic effects in many cancers, for example, prostate cancer, glioma, non-small cell lung carcinoma and acute myeloid leukemia." (PMID 34898351, 2021). "Knockdown of the β-catenin gene reverses the oncogenic effect of DIXDC1 to some extent, suggesting that DIXDC1 may promote the growth of acute myeloid leukaemia cells through upregulation of the Wnt/β-catenin signalling pathway." (PMID 36224652, 2022).
autism (2 papers, 2015 to 2023). Persistent deficits in social interaction and communication and interaction as well as a markedly restricted repertoire of activity and interest as well as repetitive patterns of behavior. "Within the developing neocortex, Dixdc1 has been shown to play a role in neuronal proliferation and migration, and dendritic development and synapse function, and multiple sequence-disrupting single nucleotide variants in DIXDC1 have been associated with mental illness and autism." (PMID 36816119, 2023). "Some have been associated with neurodevelopmental disorders: schizophrenia (DIXDC1, ARVCF, MAGI2, ZIC2), ADHD (attention deficit/hyperactivity disorder) (TCERG1L), movement disorders (NOL3, TP53INP2), Huntington’s disease (H2AFY2, AGPAT1), Parkinson’s disease (LMX1B), and autism (PLXNA4, WNT2)." (PMID 25748564, 2015).
colon cancer (2 papers, 2015 to 2022). "Our previous study showed that overexpression of DIXDC1 can be observed in colorectal carcinoma and gastric carcinoma, and can increase the proliferation of colon cancer cells and the invasion and migration ability of gastric cancer cells." (PMID 26689843, 2015). "However, Dixdc1 acts as a positive regulator in the Wnt pathway, and its overexpression could promote the proliferation and invasion of colon cancer cells." (PMID 35565775, 2022). "Recent studies have shown that overexpression of DIXDC1 can increase the proliferation of colon cancer cells and the invasion and migration ability of non-small cell lung cancer (NSCLC), both of which are affected by the PI3 K/AKT pathway." (PMID 26689843, 2015).
gastric cancer (2 papers, 2015 to 2025). A primary or metastatic malignant neoplasm involving the stomach. "Our previous study showed that DIXDC1 is overexpressed in gastric cancer (37/66) and that the upregulation of DIXDC1 is associated with poor prognosis." (PMID 26689843, 2015). "DIXDC1 is associated with biologically more aggressive phenotypes of gastric carcinoma, and DIXDC1-positive expression is an independent biomarker for poor prognosis, especially in intestinal-type gastric carcinoma." (PMID 26689843, 2015). "In previous studies, miR-154-5p was found to inhibit the growth and invasion of gastric cancer cells by targeting the DIXDC1/WNT signaling pathway." (PMID 40708910, 2025). "Our previous in vitro study showed that DIXDC1 enhances β-catenin nuclear accumulation in gastric cancer cell lines." (PMID 26689843, 2015). "We also found that DIXDC1 promotes gastric cancer cell invasion and metastasis through the activation of the Wnt pathway." (PMID 26689843, 2015). "Heterogeneous expression of DIXDC1 was observed in some areas of the gastric cancer specimen, and β-catenin expression was also detected in these areas, which further validated our in vitro experiments." (PMID 26689843, 2015). "In the intestinal-type of gastric carcinoma, DIXDC1 expression was also a significant independent prognostic predictor (HR = 2.139, P = 0.036)." (PMID 26689843, 2015). "Immunohistochemical staining was performed to characterize the expression of DIXDC1 and β-catenin in archived materials from 259 cases of gastric carcinoma." (PMID 26689843, 2015). "DIXDC1 expression in gastric carcinoma was significantly correlated with the histological intestinal-type (P < 0.001), the depth of tumor invasion (P < 0.001) and the lymph node metastasis (P = 0.006)." (PMID 26689843, 2015). "We also identified significant associations between DIXDC1 expression and the depth of tumor invasion (T), lymph node metastasis (N) and disease-specific survival, which suggested that DIXDC1 plays an important role in gastric carcinoma." (PMID 26689843, 2015). "In the intestinal-type of gastric carcinoma, the disease-specific survival rate of patients with DIXDC1-positive expression was also significantly lower than that of patients without DIXDC1 expression (P < 0.001)." (PMID 26689843, 2015). "The aim of this study was to detect the expression of DIXDC1 in different histological subtypes of gastric carcinoma and to evaluate the correlation between the expression of DIXDC1 and β-catenin localization and clinicopathological parameters, including patients’ survival." (PMID 26689843, 2015). "Our study indicated that DIXDC1 is a significant independent prognostic indicator in intestinal-type gastric carcinoma that plays an important role in carcinogenesis and progression of gastric carcinoma through the Wnt signaling pathway." (PMID 26689843, 2015). "Additionally, we found that the expression of DIXDC1 was significantly correlated with histological subtype of gastric carcinoma, and it was more commonly detected in the intestinal-type (64.2 %) than in the diffuse-type (16.5 %)." (PMID 26689843, 2015). "We found that positive expression of DIXDC1 can be detected in 47.5 % of gastric carcinoma." (PMID 26689843, 2015). "As a result of expanding the sample size, we found that DIXDC1 may play an important role in carcinogenesis and progression of the intestinal-type of gastric carcinoma." (PMID 26689843, 2015). "The present study reveals, to our knowledge for the first time, that the expression of DIXDC1 is correlated with the histological subtype of gastric carcinoma, and DIXDC1 may participate in the activation of Wnt in the carcinogenesis and progression of the intestinal-type of gastric tumor." (PMID 26689843, 2015).
gastric cancer (continued). "Our previous in vitro experiments showed that DIXDC1 interacted with β-catenin, inhibited the phosphorylation of β-catenin and increased the translocation of β-catenin to the nucleus in a gastric carcinoma cell line, indicating that DIXDC1 could positively regulate the Wnt signaling pathway." (PMID 26689843, 2015). "Cytoplasmic/nuclear localization of β-catenin was observed more frequently in the cases with positive DIXDC1 expression than those without DIXDC1 expression in intestinal-type gastric carcinoma." (PMID 26689843, 2015). "While our previous study showed that DIXDC1 enhances β-catenin nuclear localization in vitro, this has not been verified in gastric carcinoma tissues." (PMID 26689843, 2015).
lymph node metastasis (2 papers, 2015 to 2021). "In the intestinal-type group, DIXDC1 expression was associated with age (≥60 years), tumor size (≥5 cm), differentiation, the depth of invasion, lymph node metastasis and clinical stage." (PMID 26689843, 2015). "Reportedly, DIXDC1 is high-expressed in GC and is linked to advanced TNM stage, lymph node metastasis and poor prognosis." (PMID 34898351, 2021). "In the intestinal-type, but not in the diffuse-type, DIXDC1 positive expression was correlated with age (≥60 years, P = 0.018), size (≥5 cm, P = 0.036), tumor differentiation (P = 0.003), the depth of invasion (P < 0.001), the lymph node metastasis (P < 0.001) and the clinical stage (P = 0.003)." (PMID 26689843, 2015).
prostate carcinoma (2 papers, 2020 to 2021). A carcinoma that arises from epithelial cells of the prostate gland. "Additionally, miR-1271 expression was downregulated in prostate cancer tissues and its elevation remarkably hindered the progression of prostate cancer by negatively regulating the expression of its target gene DIX domain containing 1 (DIXDC1)." (PMID 32448371, 2020).
melanoma (1 paper, 2021). A malignant, usually aggressive tumor composed of atypical, neoplastic melanocytes. "Moreover, it was noted that miR-488-5p is downregulated in melanoma and that the ectopic introduction of miR-488-5p was determined to induce apoptosis and inhibit anchorage-independent cell growth via targeting DIX domain-containing 1 (DIXDC1), a pro-survival and -metastatic factor." (PMID 33435156, 2021).
schizoaffective disorder (1 paper, 2020).
cancer (9 papers, 2015 to 2024). A tumor composed of atypical neoplastic, often pleomorphic cells that invade other tissues. "Reduced DIXDC1 expression promotes malignant behavior and is associated with the survival in cancer." (PMID 35600360, 2022). "Dixdc1, a gene that encodes a transcription factor that is a positive regulator of the Wnt signaling pathway, was up-regulated in the Hedgehog-activation group, and recent studies have shown that inhibition of Dixdc1 protein can suppress the proliferation of cancer cells." (PMID 29311816, 2017). "Disheveled-Axin domain containing 1 (DIXDC1) is considered to have an involvement in the development and progression of cancers and was found in a study to be highly expressed in PCa." (PMID 39267821, 2024). "DIXDC1 is ubiquitously expressed and extensively studied in various types of cancer and uncontrolled DIXDC1 expression increases tumor size and metastasis and leads to a poor prognosis." (PMID 35144597, 2022). "Low expression of MAM domain containing 2 encoded by MAMDC2, has been associated with tumour necrosis and invasion, while an over-expression of DIX domain containing 1 regulated by DIXDC1, has been shown to have a positive effect of suppressing cancer cell migration and invasion." (PMID 27341628, 2016). "Low DIXDC1 expression significantly correlated with decreased NSCLC patient overall survival suggesting that the MARK kinase family and DIXDC1 are important clinical biomarkers in cancer." (PMID 26196184, 2015).
tumor (7 papers, 2015 to 2025). "In this study, we analyzed the co-localization of DIXDC1 and β-catenin in the tumor specimens to verify our in vitro results." (PMID 26689843, 2015). "DIXDC1 was detected mainly in the cytoplasm of the tumor cells and displayed a diffuse pattern." (PMID 26689843, 2015). "It was reported that DIXDC1 deletion enhances SNAIL-dependent gene expression, which enhances invasion and remodeling of the tumor microenvironment." (PMID 35600360, 2022). "Indeed, a number of these genes have been identified as candidate tumor suppressor genes including CREBRF, DIXDC1, AHNAK and TNS2." (PMID 28122328, 2017).
DIXDC1 also shares sentences with these, for which no sentence is quoted: depression (3 papers); bladder cancer (2); colorectal carcinoma (1); gastric tumor (1); glioma (1); Huntington disease (1); Lissencephaly (1); mental illness (1); metastasis (1); movement disorder (1); neurodevelopmental disorder (1); non-small cell lung carcinoma (1); Parkinson disease (1); rectal cancer (1); schizophrenia (1).